TMPRSS2 (transmembrane serine protease 2)
Diseases named in the same sentence as TMPRSS2 in open-access papers (continued):
Sharing a sentence is not in itself a finding about the gene and the disease.
COVID-19 (continued). "Exome sequencing and analysis of a smaller cohort of 131 COVID-19 patients from Italy for genetic variants of TMPRSS2, PCSK3, DPP4, and BSG genes identified 17 variants." (PMID 33092637, 2020). "In TMPRSS2 gene, we observed a significant difference in the frequency of c.331G>A, c.23G>T, and c.589G>A variant alleles in COVID-19 patients, compared to the corresponding allelic frequency in GnomAD." (PMID 32867305, 2020). "Here, we have analyzed the genetic markers of the TMPRSS2 gene and the differences in their alternative allele frequencies (AFs) among populations to identify possible susceptibility loci to COVID-19 and to correlate them with disease epidemiology." (PMID 32849840, 2020). "In spite of that, our data-driven approach based on a gold-standard data set from DisGeNET was able to infer the association of ACE2 and TMPRSS2 with COVID-19 with “medium” confidence, which suggests that our approach is efficacious." (PMID 33055059, 2020). "Genistein downregulated the inflammation-induced increase in SGLT1 and TMPRSS2, which may help lower the postprandial glycaemic response and COVID-19 risk or severity in healthy individuals and those with metabolic disorders." (PMID 40227199, 2025). "We hypothesized that ADT would reduce TMPRSS2 expression in lung tissue, potentially providing a mechanistic explanation for differential COVID-19 susceptibility." (PMID 41150771, 2025). "Higher TMPRSS2 expression in males, African Americans, and diabetics may lead to increased susceptibility and worse COVID-19 outcomes." (PMID 40297833, 2025). "Genetic differences in TMPRSS2 may affect people’s susceptibility to COVID-19, underscoring the need for studies that consider diverse populations." (PMID 39858469, 2025). "Given that ACE2 is highly expressed in the gut and contributes to the pathophysiology of type 2 diabetes, and co-expression of TMPRSS2 with ACE2 is implicated in the pathophysiology of COVID-19, we also examined the effects of glucose, inflammation and phytochemicals on TMPRSS2." (PMID 40227199, 2025). "Furthermore, a correlation analysis of COVID-19 and healthy PBMNCs revealed a potential association (r = 0.24; p = 0.026) between TMPRSS2 and ACE2." (PMID 40055791, 2025). "The conflicting associations of the rs12329760 variant in TMPRSS2 (a missense substitution, V160M) with COVID-19 severity across populations may reflect a complex interplay of genetic, hormonal, and virological factors." (PMID 40543387, 2025). "In summary, the role of TMPRSS2 gene variants in COVID-19 severity appears multifaceted." (PMID 40543387, 2025). "Understanding the link between TMPRSS2 expression and testosterone signaling may provide insights into gender discrepancies reported in COVID-19 susceptibility and outcomes, particularly among male patients." (PMID 40297833, 2025). "This study aimed to assess whether the expression of ACE2 and TMPRSS2 is associated with susceptibility to and severity of COVID-19 across age groups." (PMID 40729397, 2025). "In conclusion, our study revealed that the TMPRSS2 rs75603675 gene variant may induce an amino acid change from glycine to valine, which is more frequent in patients with COVID-19 who die." (PMID 38601158, 2024). "Thus, we carried out case–control research to assess the contribution of the TMPRSS2 p.(Val197Met) gene variant to the susceptibility and severity of COVID-19." (PMID 38254046, 2024). "Speculations about the potential association between ACE2 and TMPRSS2 gene variants and the cytokine response in COVID-19 have been made." (PMID 38855114, 2024). "Furthermore, the correlation of rs17854725 SNV in the TMPRSS2 gene with inflammatory cytokines and chemokines in COVID-19 patients supports previous data, suggesting its association with disease severity." (PMID 38855114, 2024). "The presence of functional ACE2 and TMPRSS2 genetic polymorphisms that affect gene expression may affect the risk of severe form of COVID-19 and its fatal outcome." (PMID 39744525, 2024).
COVID-19 (continued). "The expression of ACE2 and TMPRSS2 in the nasal endothelium of neonates, whether at term or preterm, is lower than that of adults, which may explain the mildness of neonatal COVID-19 due to the Omicron variant." (PMID 39278913, 2024). "Interestingly, while the S1/S2 cleavage site of SARS-CoV-2 has mutated throughout the course of the COVID-19 pandemic, the S2′ site, which TMPRSS2 is able to cleave, has remained unaltered." (PMID 38932275, 2024). "Our goal was to ascertain whether there was a connection between the severity of COVID-19 in the Egyptian population and the TMPRSS2 rs12329760 variant." (PMID 38263160, 2024). "Therefore, with the collective information from these three important genes (ACE2, TMPRSS2 and Furin) we modelled COVID-19 susceptibilityof South Asia in between these two major ancestries with an inclination towards West Eurasia." (PMID 38570613, 2024). "SARS-CoV-2 has tropism for the choroid plexus epithelium, meninges, and brain vasculature as the SARS-CoV-2 entry proteins ACE2 and TMPRSS2 are both expressed at these sites, which has been suggested as the underlying mechanism of dysregulated CSF hydrodynamics seen in COVID-19." (PMID 38299114, 2024). "Since viral miRNAs influence the expression of a number of genes, including genes related to ACE2 or TMPRSS2, during the progression of the COVID-19 disease, they typically cause an increase in the inflammatory response as well as an increase in clinical symptoms." (PMID 37559103, 2023). "The severe acute respiratory syndrome coronavirus 2 (SARS-CoV-2) infection is initiated after type 2 transmembrane protease (TMPRSS2) cleaves the viral spike glycoprotein, which then binds to the angiotensin-converting enzyme 2 (ACE-2) receptor." (PMID 37097586, 2023). "Similarly, G allele in TMPRSS2 (rs2070788) in female cases was associated with an increased risk of developing severe COVID-19." (PMID 37287057, 2023). "Interestingly, TMPRSS2 gene single-nucleotide polymorphism (SNP) rs12329760 causing V160M mutation in TMPRSS2-SRCR domain is associated with severe COVID-19 disease progression, suggesting that the SRCR domain impacts SARS-CoV-2 pathogenicity." (PMID 37896901, 2023). "Our finding adds new insight to the literature on the role of TMPRSS2 in COVID-19 severity and point to the ethnic-specific risk alleles and hidden unknown complexity behind the host genetic susceptibility to SARS-CoV-2 infection." (PMID 36795725, 2023). "In addition, several authors have assessed the influence of genetic variants of TMPRSS2, finding that some SNPs such as rs12329760 or rs75603675 are associated with COVID-19 severity." (PMID 37809329, 2023). "An increase in ACE-expressing EVs in COVID-19 patients with severe disease and a trend of increased TMPRSS2 may be indicative of the loss of ACE on the cell surface which leads to endothelial injury and facilitates inflammation." (PMID 36982991, 2023). "Therefore, this study evaluated the association between TMPRSS2 and coronavirus disease 2019 (COVID-19) mortality." (PMID 36457338, 2022). "Moreover, it was demonstrated that TMPRSS2 rs12329760 had a predictive value for identifying individuals at risk of developing severe COVID-19." (PMID 36457338, 2022). "In SARS-CoV-2–infected individuals, both the alternate allele of rs2285666 for ACE2 gene and the SNP (rs12329760) of TMPRSS2 polymorphisms may serve as predictive model for COVID-19 severity." (PMID 36072602, 2022). "On the other hand, high testosterone levels might increase susceptibility and severity of COVID-19 through augmentation of TMPRSS2, which is crucial for cleaving and activation of SARS-CoV-2 spike protein during acute SARS-CoV-2 infection." (PMID 35806986, 2022). "Intended as a pilot study, the results should be interpreted as such, and further studies evaluating the association of ACE2 and TMPRSS2 levels and disease course and outcome in larger cohorts of COVID-19 patients would be needed as external validation of our findings." (PMID 35455738, 2022).
COVID-19 (continued). "In this study, we sought to ascertain whether the serum concentrations of ACE2 and TMPRSS2 soon after hospital admission may be associated with the need for MV in adult COVID-19 patients." (PMID 35455738, 2022). "The first whole-genome investigation in 322 Chinese patients infected with COVID-19 revealed a decreased allele frequency of the TMPRSS2 rs12329760 variant in patients with severe disease than patients with moderate disease, demonstrating the critical role of TMPRSS2 in progression of COVID-19." (PMID 36457338, 2022). "Ultimately, we identified 10 SNPs and 21 mutations in the ACE2 gene, along with 13 SNPs and 12 variants in the TMPRSS2 gene, which may be associated with COVID-19." (PMID 35193695, 2022). "Thus, the present study aimed to evaluate the association of the TMPRSS2 polymorphisms with COVID-19." (PMID 36146782, 2022). "Accordingly, since ACE2 and TMPRSS2 polymorphisms have been associated with severe COVID-19, it would be plausible that these polymorphisms could also exhibit an association with post-COVID symptomatology, particularly fatigue and dyspnea." (PMID 36360172, 2022). "In summary, our results, using survival analysis, demonstrated for the first time that older individuals carrying the rs2070788 GG genotype in the TMPRSS2 gene, previously associated with elevated expression levels in lung tissue, have a higher risk of COVID-19 death." (PMID 36423166, 2022). "Therefore, we investigated the expression and distribution of ACE2 and TMPRSS2 in the thyroid gland to identify the histological mechanism underlying thyroid disorder-related COVID-19." (PMID 35625425, 2022). "Changes in TMPRSS2 expression levels caused by single nucleotide polymorphisms (SNPs) may contribute to the outcome of COVID-19." (PMID 36423166, 2022). "Thus, it is plausible that the rs12329760/TMPRSS2 T allele further increases TMPRSS2 expression in females, increasing the odds of severe forms of COVID-19." (PMID 36672770, 2022). "Considering the variability in frequencies of the TMPRSS2 polymorphisms reported associated with COVID-19, we determine only those with possible functional effects and high frequency in a Mexican population from Los Angeles reported previously in a bioinformatics analysis." (PMID 36146782, 2022). "We aimed to evaluate whether serum ACE2 and TMPRSS2 levels are associated with adverse outcomes in COVID-19, and specifically the need for MV." (PMID 35455738, 2022). "The ACE2/ADAM17/TMPRSS2 interplay has been suggested as the main risk factor for COVID-19." (PMID 35887687, 2022). "Genetic variants of TMPRSS2 augmenting TMPRSS2 activity might play an important role in the progression of COVID-19 severity and may be considered as a genetic risk factor." (PMID 35250581, 2022). "Nevertheless, our data represents an advance in biomedical science because it shows the power of ACE2 (rs2285666) and TMPRSS2 (rs12329760) gene polymorphisms to predict COVID-19-related disease severity that, in addition to routine cell and serum markers, explains 86% of the severity." (PMID 35996506, 2022). "Targeting miRNAs associated with immune responses and regulating ACE2, TMPRSS2, and spike protein expressions may also provide an effective treatment approach against COVID-19." (PMID 36293144, 2022). "Increased attention to polymorphisms in ACE2 or TMPRSS2 may aid in determining the most successful COVID-19 therapy regimen (i.e., hydroxychloroquine and camptothecin)." (PMID 35193695, 2022). "During membrane fusion, SARS-CoV-2 “S” protein is activated by the TMPRSS2; therefore, it is postulated that TMPRSS2 variants might have been correlated to COVID-19 severity." (PMID 35250581, 2022). "Recently, the AR-inducible gene, transmembrane protease serine 2 (TMPRSS2), was identified as a critical host viral entry factor for severe acute respiratory syndrome coronavirus 2 (SARS-CoV-2), the virus that causes coronavirus disease 2019 (COVID-19)." (PMID 35328625, 2022).
COVID-19 (continued). "As this work was designed as a pilot study, it is possible that larger cohorts might yield statistically significant results regarding serum TMPRSS2 levels as a potential early biomarker for risk stratification in COVID-19." (PMID 35455738, 2022). "We conclude that genetic variants within ACE1, ACE2 and TMPRSS2 may be potential biomarkers of COVID-19 severity, which needs to be further confirmed in a larger set of studies." (PMID 35949487, 2022). "Here, we performed a systematic review, based on guidelines of the Preferred Reporting Items for Systematic Reviews and Meta-Analyses (PRISMA) criteria, with the aim of assessing whether polymorphisms in ACE2 and TMPRSS2 genes affect the COVID-19 condition." (PMID 35193695, 2022). "Despite the functional significance of Tmprss2 in COVID-19 pathogenesis, the molecular mechanisms underlying its endogenous regulation remain largely unknown." (PMID 35301316, 2022). "Indeed, the possible role of androgen receptors in increasing SARS-CoV-2 infection through the regulation of TMPRSS2 transcription has recently emerged, suggesting crosstalk between COVID-19 and prostate cancer, caused by the elevated expression of TMPRSS2." (PMID 34201505, 2021). "The COVID-19 pandemic requires special attention on patients affected by GI tumors—malignancies more common in the elderly—who already have higher ACE-2 and TMPRSS2 expression and are more likely to be affected by other comorbidities that make them more susceptible to severe forms of COVID-19." (PMID 34399734, 2021). "Possible changes in TMPRSS2 function and/or structure due to the Val160Met substitution might explain our findings on the association of this SNP with the viral load in COVID-19 patients." (PMID 34001248, 2021). "In this regard, treatment strategies to block TMPRSS2 increase have been proposed, since TMPRSS2 expression could affect COVID-19 susceptibility and severity." (PMID 34204890, 2021). "In the present study, we compared the expression levels of ACE2 and TMPRSS2 at the resection margins of lung cancer patients as well as in normal tissues of non-cancer individuals to investigate the susceptibility of lung cancer patients to COVID-19." (PMID 34094930, 2021). "A risk effect for TMPRSS2 levels on COVID-19 severity could be expected once this enzyme triggers the viral S protein priming after its recognition by ACE2 entry receptor and is considered an important player host susceptibility to SARS-CoV-26." (PMID 33958627, 2021). "Remarkably, the TMPRSS2 has a highly variable expression in humans and its expression may be positively associated with COVID-19 severity." (PMID 34527703, 2021). "Among the proteases, TMPRSS2, Cathepsin L, and Furin mRNA were upregulated in the kidney of DHT-treated female mice suggesting an increased susceptibility to SARS-CoV-2 renal infection in women with PCOS." (PMID 33922918, 2021). "Similarly, an association between increased COVID-19 severity in males and expression of TMPRSS2, which is involved in cellular entry of the virus, has been theorized." (PMID 34595175, 2021). "In conclusion, these data indicate that the HFS diet increases body weight, insulinemia RAS hyperactivation and lung ACE2 and TMPRSS2, which could explain the predisposition of obese individuals to severe COVID-19 outcomes." (PMID 34684358, 2021). "According to ACE2 and TMPRSS2 variants, the African populations could have a lower susceptibility to COVID-19 than East and South Asians." (PMID 33868239, 2021). "Therefore, the expression of ACE2 and TMPRSS2 is assumed to be associated with host susceptibility to and severity of COVID-19." (PMID 33981629, 2021). "Furthermore, genome-wide association studies have shown that FURIN and TMPRSS2 had significant genetic variants prevalent in COVID-19 patients, suspecting a role in susceptibility to infection." (PMID 34578338, 2021).
COVID-19 (continued). "In fact, higher TMPRSS2/ACE2 ratios showed a prominent risk effect for respiratory distress requiring oxygen therapy during COVID-19 and comparisons between multiple models revealed that TMPRSS2/ACE2 ratio can be even more informative to model disease severity than ACE2 expression alone." (PMID 33958627, 2021). "Because ACE2 and TMPRSS2 are co-expressed in such patients, they may be extremely susceptible to COVID-19." (PMID 33706759, 2021). "As camostate mesilate or other TMPRSS2 inhibitors administered in higher doses or during the very early phase of COVID-19 might be effective in lowering the risk of disease progression, additional studies are needed." (PMID 34391321, 2021). "Moreover, sex hormonal regulation was found to regulate ACE2 and TMPRSS2, resulting in differential gender susceptibility to COVID-19." (PMID 33777332, 2021). "Therefore, in this study, we focused on studying the association between the p.Val160Met variant of the TMPRSS2 gene and the severity, viral load and clinical outcomes of COVID-19 patients." (PMID 34001248, 2021). "Therefore, in this study, we investigated the correlation between a genetic variant within the human TMPRSS2 gene and COVID-19 severity and viral load." (PMID 34001248, 2021). "Notably, a strong risk effect of TMPRSS2/ACE2 ratios on COVID-19 severity was found (adjOR = 4.28; 95%CI = 1.36–13.48)." (PMID 33958627, 2021). "Our data are consistent with previous reports on TMPRSS2 polymorphisms and COVID-19 severity." (PMID 34001248, 2021). "TMPRSS2 is a protease involved in SARS-CoV-2 entry into cells via priming of S protein; TMPRSS2 overexpression might result in a higher number of infected cells that could potentially augment COVID-19 susceptibility in DS." (PMID 33660221, 2021). "TMPRSS2 is regulated by androgens, which may explain the higher susceptibility of men to suffer from severe forms of COVID-19." (PMID 33013675, 2020). "In theory, the variation in the expression of TMPRSS2 between males and females may serve as a predisposing factor leading to increased risk of COVID-19-associated mortality in males." (PMID 33117174, 2020). "Thus, in a previous study, the genetic polymorphisms affecting the expression level of the TMPRSS2 gene have been suggested as novel candidates in the severity of COVID-19 in Italy." (PMID 33396837, 2020). "Coronavirus disease 2019 (COVID-19) is caused by SARS-CoV-2, an emerging virus that utilizes host proteins ACE2 and TMPRSS2 as entry factors." (PMID 33046696, 2020). "The oncogenic roles of TMPRSS2 may be linked to poor outcomes with COVID-19 as well, while the localization of the gene on 21q22.3 could place individuals with Down syndrome at high risk for COVID-19 infection." (PMID 33092637, 2020). "Androgen regulation of TMPRSS2 expression may also provide a mechanistic explanation for the observation that male sex is associated with a higher COVID-19 case fatality rate than female sex, but again, experimental validation would be required." (PMID 33312454, 2020). "A research group in Italy also reported that ACE2 and TMPRSS2 variants and expression could contribute to the different severities of COVID-19." (PMID 32973879, 2020). "This study aims to propose possible variants in the regulatory regions of ACE2 and TMPRSS2 that may underlie the marked geographic and race variations in COVID-19 prevalence and mortality." (PMID 33195331, 2020). "Recently, A1AT has been found to inhibit severe acute respiratory syndrome coronavirus 2 (SARS-CoV-2) infection by inhibiting transmembrane serine protease 2 (TMPRSS2), a protease involved in the entry of SARS-CoV-2 into host cells." (PMID 33362565, 2020). "This hypothesis agrees with epidemiological data that show higher COVID-19 prevalence and mortality rates in Europe and the Americas (with a greater frequency of high-TMPRSS2 expression-associated alleles)." (PMID 32849840, 2020).